MAOB (monoamine oxidase B)
Diseases named in the same sentence as MAOB in open-access papers (continued):
Sharing a sentence is not in itself a finding about the gene and the disease.
Parkinson disease (continued). "Especially for symptoms of Parkinson’s and Alzheimer’s diseases, MAO-B (Monoamine oxidase B) inhibitors are generally used." (PMID 31261693, 2019). "Selegiline, a Monoamine oxidase B (MAO-B) inhibitor with neuroprotective and antioxidant effects, is utilized for the oral therapy of Parkinson’s disease, Alzheimer’s disease, depression, narcolepsy and cocaine addiction." (PMID 30781585, 2019). "For instance, ACS84 prevented neuronal death in the substantia nigra and inhibited lipid peroxidation, oxidative stress, and monoamine oxidase B (MAO-B) activity, thereby improving motor performance and surpassing the effects of NaHS and L-DOPA in Parkinson’s disease models." (PMID 41465271, 2025). "Additionally, GNR-E extract exhibited a stronger inhibitory activity toward monoamine oxidase-B (MAO-B) than monoamine oxidase-A (MAO-A), suggesting its potential relevance to dopaminergic regulation, cognitive impairment and Parkinson’s disease." (PMID 41375361, 2025). "In contrast to rasagiline’s efficacy in Parkinson disease, this was independent of existing variances in the MAOB and DRD1 genes." (PMID 38474416, 2024). "Inhibitors of monoamine oxidase B (MAO-B) and catechol-O-methyltransferase (COMT) are major strategies to reduce levodopa degradation and thus to increase and prolong its effect in striatal dopaminergic neurotransmission in Parkinson’s disease patients." (PMID 36964457, 2023). "CHRNA4, MAOB and CHRM2 are targets for the treatment of Parkinson’s disease." (PMID 35566179, 2022). "Selegiline (L-deprenyl), an irreversible inhibitor of monoamine oxidase-B (MAO-B), a therapeutic agent of Parkinson's disease, is known to have neuroprotective properties that may involve its regulatory effects on antioxidant enzymes." (PMID 22536538, 2012). "Rasagiline, a new drug developed to treat Parkinson's disease, is known to inhibit monoamine oxidase B. However, its metabolite R-(-)-aminoindan does not show this kind of activity." (PMID 21338509, 2011). "A combination with the monoamine oxidase B (MAO-B) inhibitor, selegiline, may increase the bioavailability of betahistine to levels similar to the well-established combination of L-DOPA with carbidopa or benserazide in the treatment of Parkinson's disease." (PMID 37920833, 2023). "The human acetylcholine esterase (AChE, PDB ID: 4M0E), monoamine oxidase B (MAO-B; PDB ID: 6FVZ), and Polo-like kinase-2 (PLK2; PDB ID: 4I5P) were selected as three possible pharmacological target proteins for IR3G and IR in the pathway of neuroprotective and anti-Parkinson’s activities." (PMID 35270118, 2022).
Alzheimer disease (107 papers, 2013 to 2026). A progressive, neurodegenerative disease characterized by loss of function and death of nerve cells in several areas of the brain leading to loss of cognitive function such as memory and language. "While historically linked to neurodegenerative disorders, where MAOB deficiency contributes to neuronal dysfunction in Alzheimer’s disease." (PMID 40821817, 2025). "Pathway analysis identified monoamine oxidase B as a key target involved in serotonergic synapse dysfunction related to Alzheimer’s disease." (PMID 40076984, 2025). "The usage of dual acetylcholinesterase (AChE) monoamine oxidase B inhibitors is a novel strategy in treating Alzheimer's disease." (PMID 41181006, 2025). "Beyond monoamine oxidase-B inhibitors, several emerging therapeutic strategies for Alzheimer’s disease (AD) have been proposed, reflecting the complex and multifactorial nature of the disorder." (PMID 41008652, 2025). "Another enzyme that has been identified playing an important role in the pathophysiology of Alzheimer’s disease (AD) is monoamine oxidase B (MAO-B)." (PMID 38203753, 2024). "Monoamine oxidase B (MAO-B) can produce ROS to directly damage neuronal cells, which is a possible target for the treatment of Alzheimer’s disease." (PMID 37570873, 2023). "In this study we investigate the capability of a novel monoamine oxidase B (MAO-B) PET ligand to monitor reactive astrogliosis in a transgenic mouse model of Alzheimer`s disease (AD)." (PMID 36906584, 2023). "GABA released from reactive astrocytes affects nearby neurons, and increased enzyme activity of MAOB has been reported in neurodegenerative disease models such as Parkinson’s disease and Alzheimer’s disease." (PMID 36531137, 2022). "Monoamine oxidase is critically related to amyloid plaque formation in Alzheimer’s disease patients, and monoamine oxidase B is expressed at high levels in the brain of patients with Alzheimer’s disease." (PMID 35630702, 2022). "The synergisticinhibition of monoamine oxidase B (MAO B) and acetylcholinesterase(AChE) is believed to provide a potentiated effect in the treatmentof Alzheimer’s disease." (PMID 35300078, 2022). "We found significant concentration differences in several amino acids, acylcarnitines and polyamines linking delirium-prone patients to known factors in Alzheimer’s disease such as monoamine oxidase B (MAOB) protein." (PMID 34017039, 2021). "MAOB regulates the expression of β-amyloid, which is a key molecule in the pathogenesis of Alzheimer’s disease." (PMID 34451413, 2021). "For example, ladostigil is a dual cholinesterase–monoamine oxidase-B (MAO-B) inhibitor currently being researched for the treatment of Alzheimer's disease and other neurodegenerative diseases." (PMID 32232029, 2020). "Cognitive dysfunction in Alzheimer’s disease results from a complex interplay of various pathological processes, including the dysregulation of key enzymes such as acetylcholinesterase (AChE), butyrylcholinesterase (BuChE), and monoamine oxidase B (MAO-B)." (PMID 39883631, 2025). "Monoamine oxidase-B (MAO-B), acetylcholinesterase (AChE), and butyrylcholinesterase (BChE) have been considered target enzymes of depression and neurodegenerative diseases, including Alzheimer’s disease (AD)." (PMID 36678580, 2023). "Moreover, the literature points out that berberine has inhibitory effects on four key enzymes related to the pathogenesis of Alzheimer s disease: monoamine oxidase B (MAO-B), acetylcholinesterase, monoamine oxidase A (MAO-A), and butyrylcholinesterase." (PMID 35668943, 2022). "Moreover, MAOB activity is also found to be elevated in Alzheimer’s disease patients." (PMID 29899283, 2018). "Monoamine oxidase B (MAO-B), acetylcholinesterase (AChE), and butyrylcholinesterase (BChE) are important targets for drugs used in the treatment of Alzheimer’s disease." (PMID 39859562, 2025).
Alzheimer disease (continued). "The compound is known for its dual action in Alzheimer's Disease (AD), with IC50 values of 37.1 and 31.8 uM for AChE and MAOB, respectively." (PMID 38790018, 2024). "A monoamine oxidase B (MAO-B) selective positron emissiontomography(PET) tracer [11C]-deuterium-l-deprenyl holdspromise for imaging reactive astrogliosis in neurodegenerative diseases,such as Alzheimer′s disease (AD)." (PMID 38133820, 2024). "Moreover, the expression of monoamine oxidase B (MAO‐B), a key enzyme for astrocytic GABA synthesis and GABA activity, was reported to be significantly increased in reactive astrocytes in rodent models of ischaemic stroke and Alzheimer's disease." (PMID 37702572, 2024).
depression (95 papers, 2011 to 2026). "In contrast, monoamine oxidase-B (MAO-B) inhibitor use was associated with relatively fewer depression symptoms across all years (β=−0.41, 95%CI [−0.81,−0.01], p=0.047)." (PMID 37425947, 2023). "Monoamine oxidase B (MAO-B) is a critical protein implicated in Depression and PD." (PMID 39444620, 2024). "In addition, the rs1799836 variant in the monoamine oxidase B (MAO-B) gene increased the risk for severity of depression and the presence of anhedonia, but only when combined with ACE." (PMID 37887445, 2023). "In the Flinders Sensitive Line (FSL) rat model of depression, reactive astrocytes exhibit increased activity of the monoamine oxidase-B (MAO-B) enzyme, leading to an excessive synthesis and release of GABA." (PMID 40650814, 2025). "The effectiveness of PEA in improving mood in depression cases treated with a selective MAO-B inhibitor is attributable to its high sensitivity to monoamine oxidase B." (PMID 41155669, 2025). "MAOB is reported to play a role in the pathogenesis and therapy of depression, and effects are exerted through inhibiting MAO and degradation of 5-HT and suppressing the production of H2O2." (PMID 36045664, 2022). "The role of Praxol, an antidepressant drug recommended in the clinical guidelines, on MPTP-induced PD-related depression was only mentioned when compared to the antidepressant effect of Selegiline, a monoamine oxidase B (MAOB) inhibitor." (PMID 35645772, 2022). "In silico analysis showed that most flavonoids have high docking scores for monoamine oxidase A (MAOA) and monoamine oxidase B (MAOB), which are two important drug targets in depression." (PMID 35052561, 2021). "Individual compounds from flavonoids and carotenoids have been tested for mechanisms in important drug targets, MAO (MAOA and MAOB) and BDNF, which are known to be associated with depression through molecular docking studies for possible inhibitory roles." (PMID 35052561, 2021). "A recent study used CD157 KO mice, a PD genetic model displaying depression- and anxiety-like behaviors, to explore the antidepressant and anxiolytic effects of selegiline, an irreversible monoamine oxidase-B (MAO-B) inhibitor." (PMID 29158943, 2017). "Tricyclic anti-depressants (TCAs), selective serotonin receptor inhibitors (SSRIs), serotonin and norepinephrine reuptake inhibitors (SNRIs), and monoamine oxidase B (MAO B) inhibitors are some of the most commonly investigated groups of drugs for depression in PD patients." (PMID 38380213, 2024). "The present study investigated the effects of monoamine oxidase A (MAO-A) rs1465107 and monoamine oxidase B (MAO-B) rs1799836 gene variants, in conjunction with adverse childhood experiences (ACEs), on the susceptibility and severity of major depressive disorder (MDD)." (PMID 37887445, 2023). "However, deficiency of serotonin can lead to depression, so MAOA and MAOB were two important targets for DD." (PMID 34306154, 2021). "One pharmacological explanation for the influence of smoking on depression is that a reduction in monoamine oxidase B (MAO B) activity might synergize with nicotine to produce the diverse behavioral and epidemiological effects of smoking." (PMID 22938088, 2012). "Another factor that may inhibit the realization of stable treatment may be the narrowing of treatment options for PD in patients with depression, as the concomitant use of monoamine oxidase B inhibitors, one of the major anti-PD drug classes, with antidepressants is contraindicated in such patients." (PMID 40276471, 2025). "Hence, the MAOA and MAOB gene polymorphisms seem not to significantly affect depression in PD patients." (PMID 37374342, 2023). "In addition, it was found that 1-[2-(4-Benzyloxyphenoxy) Ethyl] Imidazole could also improve the motor and depression symptoms of MPTP-induced mice by inhibiting MAOB." (PMID 35645772, 2022).
depression (continued). "Selegiline, also known as R-deprenyl (Jumex®), is a registered, irreversible and selective monoamine oxidase B (MAO-B) enzyme inhibitor found to be effective and well-tolerated in the treatment of Parkinson’s disease (PD) and depression." (PMID 40512245, 2025). "Ladostigil is a dual cholinesterase (ChE) and brain-selective monoamine oxidase-A (MAO-A) and monoamine oxidase-B (MAO-B) inhibitor, indicated for the treatment of dementia, comorbid with extrapyramidal disorders and depression." (PMID 37259302, 2023). "MAOA and MAOB are crucial target genes of various mental diseases, and MAOA is particularly important in depression and anxiety." (PMID 32182911, 2020). "This matches with the hub genes from PPI network, in which EGFR has been proved to be a significant depression-related gene, MAOA and MAOB are crucial target genes of various mental diseases, and MAOA is particularly important in depression and anxiety." (PMID 32182911, 2020). "In conclusion, the most important bioactive components—anthraquinone, kaempferol, and vanillic acid—can alleviate depression symptoms by regulating MAOA, MAOB, and ESR1." (PMID 32182911, 2020). "The results of our study support the role of anthraquinone, kaempferol, and vanillic acid on MAOA, MAOB, and ESR1 in the etiology of depressive disorder." (PMID 32182911, 2020). "Selegiline is an irreversible monoamine oxidase-B (MAO-B) inhibitor, and is widely used in the treatment of PD and major depression." (PMID 28515684, 2017). "Others reported that platelet monoamine oxidase –B (MAO-B) activity and plasma concentration of Gamma –amino butyric acid (GABA) increased following CES, in conjunction with clinical improvement in anxiety and depression." (PMID 25927012, 2014). "The docking results of GABRA1 with naringenin and hesperidin, HCRTR1 with naringenin-7-O-glucoside, poncirenin and genipin 1-gentiobioside, and luteolin with SLC6A4, GLO1, MAOB and MTNR1A may clarify the mechanism of action of ZZHPD in treating insomnia and depression." (PMID 35095537, 2021). "Therefore, HF may improve depression symptoms by regulating including but not limited to MAOA, MAOB, AR, CAMK2A, and GAD2." (PMID 34306154, 2021). "Finally, in patients suffering from severe depression, the administration of a MAOA/MAOB inhibitor along with an oral supplementation with L-phenylalanine was reported to exert beneficial effects via a mechanism presumably involving an increase in brain β-PEA levels." (PMID 34638785, 2021). "Another study found that MAOB is related with the etiology of psychotic diseases, but not specifically for SCZ while the authors failed to prove the association between MAOB and five psychotic disorder features, such as delusions, hallucinations, mania, depression, and negative symptoms." (PMID 27992373, 2017). "Several reports have described that selegiline, a monoamine oxidase B (MAO-B) inhibitor, is effective for the treatment of decreased willingness and depressed mood in PD.Tom and Cummings recommended selegiline as the first choice to treat depression in PD patients not exhibiting suicidality." (PMID 22389809, 2011).
Dyskinesia (32 papers, 2012 to 2026). A movement disorder which consists of effects including diminished voluntary movements and the presence of involuntary movements. "Together, the MAOB (rs1799836) polymorphism predicts the development of dyskinesias in PD patients." (PMID 35096365, 2022). "Furthermore, MAOB rs1799836 has also been associated with the occurrence of dyskinesia, while DDC rs921451 and rs3837091 have been associated with the motor response to acute levodopa challenge." (PMID 30745869, 2019). "Synthetic dopamine (DA) precursors (e.g., levodopa), DA agonists (e.g., pergolide), and monoamine oxidase-B (MAO-B) inhibitors (e.g., selegiline) are frequently used to manage PD, but they can lead to serious side effects such as cardiopathy and dyskinesia." (PMID 39921688, 2025). "Clinicians often prefer levodopa-sparing strategies (e.g. non-ergot dopamine agonists (DAs) or monoamine oxidase B (MAO-B) inhibitors) as initial therapy, especially among younger patients at higher risk of motor fluctuations and dyskinesia." (PMID 35658842, 2022). "Monoamine oxidase type B (MAOB) inhibitors have elicited neuroprotective effects in preclinical models of PD and longer exposure to these inhibitors have been associated with less clinical decline in PD patients and reduced risk of dyskinesia." (PMID 29255414, 2017). "When patients experience wearing-off, the dose or number of administrations of levodopa may be adjusted, or levodopa adjunctive drugs such as a dopamine agonist (DA), monoamine oxidase B (MAO-B) inhibitor, or catechol-O-methyltransferase (COMT) inhibitor are added to avoid dyskinesia." (PMID 40529448, 2025).
Anxiety (31 papers, 2014 to 2026). Intense feelings of nervousness, tension, or panic often arise in response to interpersonal stresses. "Calcitonin gene-related peptide (CGRP) causes anxiety by modulating the HP1γKLF11-MAOB pathway, depleting dopamine in the dorsal hippocampus, and increasing MAOB while reducing dopamine levels, leading to anxiety-like behaviors." (PMID 38503899, 2024). "As MAOB loss of function may lead to decreased anxiety-like responses in rodents, the reduced response to aversive stimuli found in deprenyl-treated larvae may be considered as an anxiolytic-like effect of the hyperserotonergic phenotype." (PMID 34070577, 2021). "It was found that the knockout of the MAOB gene was able to reduce anxiety-like responses in mice through regional elevation of PEA." (PMID 40004189, 2025). "Here, we showed that injecting CGRP into the hippocampus significantly increases abundance MAOB and decreases hippocampal dopamine, thereby inducing anxiety-like behavior." (PMID 38503899, 2024). "Collectively, these results imply that CGRP induces anxiety-like behavior by reducing dopamine levels through the upregulation of MAOB expression in the dorsal hippocampus of mice." (PMID 38503899, 2024). "Furthermore, we also observed changes in MAOB expression, suggesting that increased dopamine catabolism is involved in the induction of anxiety-like behavior." (PMID 38503899, 2024). "Furthermore, infusion of CGRP (1 nmol) into the dorsal hippocampus significantly increased MAOB expression as well as anxiety-like behaviors, which were suppressed by the pharmacological inhibition or knockdown of MAOB." (PMID 38503899, 2024). "We also examined whether administration of the MAOB inhibitor selegiline (1 mg/kg, intraperitoneal administration for 3 times) suppresses the anxiety-like behavior induced by stereotaxic intrahippocampal CGRP injection." (PMID 38503899, 2024). "While our current understanding is limited, it is important to note that selegiline, a MAOB inhibitor, appears to suppress CGRP-mediated anxiety response in mice." (PMID 38503899, 2024). "To ascertain the necessity of hippocampal MAOB in CGRP-mediated anxiogenesis, we investigated the impact of MaoB knockdown on anxiety-like behaviors in mice." (PMID 38503899, 2024). "Moreover, the spatial distributions of MAOA, MAOB, COMT, and SLC6A4 on the left side of the network suggested that these genes significantly contributed to the pathogenesis of anxiety." (PMID 38684743, 2024). "Furthermore, stereotaxic injection of CGRP into the hippocampus induced anxiety-like behavior, and this effect was blocked by selegiline, a MAOB inhibitor or MaoB knockdown, suggesting a link between CGRP signaling and MAOB in the hippocampus." (PMID 38503899, 2024). "Because we found that CGRP (ICV) increases abundance MAOB in the hippocampus, we examined whether CGRP-induced anxiety behavior involves the hippocampus." (PMID 38503899, 2024).